ENTPD5 (ectonucleoside triphosphate diphosphohydrolase 5 (inactive))
Diseases named in the same sentence as ENTPD5 in open-access papers (continued):
Sharing a sentence is not in itself a finding about the gene and the disease.
Obesity (1 paper, 2025). Accumulation of substantial excess body fat. "Consistent with the amelioration of obesity, hepatic ENTPD5 overexpression increased lipolytic gene expressions in white adipose tissue (WAT) of obese mice." (PMID 40788055, 2025). "Under overnutrition condition, inhibition of hepatic ENTPD5 will trigger the excessive expression and secretion of ADM to inhibit BAT thermogenesis, causing obesity and metabolic dysfunctions." (PMID 40788055, 2025). "Targeting hepatic ENTPD5‐ADM pathway represents a novel strategy for combating against obesity and metabolic disorders." (PMID 40788055, 2025). "Inhibition of hepatic ENTPD5 expression plays important roles in the development and progression of diabetes, NAFLD, and obesity." (PMID 40788055, 2025). "Hepatic ENTPD5 overexpression ameliorates the deregulated glucolipid metabolism and obesity with increased brown adipose tissue (BAT) thermogenesis, while hepatic ENTPD5 silencing exerted the opposite effects in obese mice." (PMID 40788055, 2025).
oral cancer (1 paper, 2024). "The presence of uracil and/or expression patterns of intermediate molecules in purine and pyrimidine pathways, such asCD39, CD73, and P2Y6 receptors together with ENTPD4 and ENTPD5, hold promise as biomarker(s) for oral cancer diagnosis and prognosis." (PMID 38773214, 2024).
serous ovarian cancer (1 paper, 2022). "Dysregulation of Ectonucleoside Triphospahate Diphosphohydrolase 5 (ENTPD5) in tumors might be associated with tumor progression, while the role of ENTPD5 in the growth and metastasis of serous ovarian cancer (SOC) is still unclear." (PMID 35668504, 2022).
tubular adenoma (1 paper, 2014). A usually polypoid neoplasm arising from the glandular epithelium. "To support this finding at protein level, we investigated by IHC the expression of ENTPD5 during colorectal carcinogenesis in a series of 20 normal colic mucosa samples, 40 tubular adenomas (LG-IEN and HG-IEN), and 20 early primary stages CRCs." (PMID 25115394, 2014).
tumor (19 papers, 2006 to 2025). "Expression of the ENTPD5/mt-PCPH onco-protein and overexpression of the normal ENTPD5/PCPH protein contribute to the malignant transformation of diverse mammalian cell types, and PCPH is mutated and/or deregulated in various human tumor types." (PMID 23921441, 2013). "Previous studies have shown that the ENTPD5 is closely associated with tumor progression." (PMID 35668504, 2022). "Correspondingly, the differential expression of ENTPD4 and ENTPD5 in immune and tumor cells, respectively, indicatedtheir involvement in disease progression." (PMID 38773214, 2024). "We propose that PTEN mutation or inactivation is one means by which tumor cells become resistant to ER stress-induced apoptosis, resulting in increased ATF6 and enhanced Entpd5/IGF1R expression, promoting protein glycosylation and folding." (PMID 36824269, 2023). "The drug effects were largely restored by enforced expression of ENTPD5, validating that the diminished tumor cell motility was a result of compromised ENTPD5 activity." (PMID 37563605, 2023). "We have demonstrated that ENTPD5 was highly expressed in SOC tissues and positively associated with tumor metastasis." (PMID 35668504, 2022). "Compared to fallopian tube tissues, the expression of ENTPD5 was significantly higher in tumor tissues obtained from SOC patients, and positively correlated with clinical stage and metastasis." (PMID 35668504, 2022). "Cell quantification results showed that the difference in tumor cell count of ENTPD5 knockdown cells was statistically significant compared to the negative control after 13 days of culture (p < 0.01)." (PMID 35668504, 2022). "The results of the 3D growth model showed that ENTPD5 knockdown resulted in a significant delay in tumor growth (p < 0.01)." (PMID 35668504, 2022). "As shown by both the cell clone formation assay and FACS analysis, ENTPD5 knockdown resulted in a significant delay in tumor growth in vitro, and the cell cycle was arrested in the G0/G1 phase accompanied by a significant increase of apoptosis." (PMID 35668504, 2022). "Entpd5, a UDPase, is involved in Akt responses and has been shown to increase the catabolic efficiency of aerobic glycolysis in tumor cells." (PMID 28779178, 2017). "Among all the available parameters, sex, smoke history and tumor stages showed significant correlation to ENTPD5 scores (P < 0.05)." (PMID 25794010, 2015). "Western blotting analysis of tumor tissues showed that the protein expression of proliferating cell nuclear antigen and ENTPD5 was decreased but that of Caspase 3 was increased in ENTPD5-KD group of mice compared with control groups." (PMID 25794010, 2015). "ENTPD5 belongs to a family of UDP-hydrolyzing enzymes and has been alternatively linked, depending on the different tumor cell system analyzed, to ATP consumption as well as protein folding." (PMID 25115394, 2014). "ENTPD5 is becoming recognised as a pivotal protein in the respiratory switch to aerobic glycolysis, the Warburg effect, in many tumours." (PMID 24859727, 2014). "All tumor cell lines showed an inverse correlation (−0.85, p-value < 0.05) between high expression of miR-182 and low expression of ENTPD5." (PMID 23987127, 2013). "ENTPD5 promotes tumor proliferation through ATP consumption and favors aerobic glycolysis." (PMID 36849424, 2023). "The overexpression of ENTPD5 in melanoma cells could enhance the survival of tumor cells, resist endoplasmic reticulum stress-mediated apoptosis, and promote tumor cell metastasis." (PMID 35668504, 2022).
tumor (continued). "It seems that ENTPD5 expression may not only be a powerful reporter for the metabolic shift in tumor cells, but also a possible predictor for tumor chemotherapy responses." (PMID 25794010, 2015). "However, owing to the discrepant results obtained in the different tumor types, the molecular functions played by ENTPD5 protein in CRC deserve further investigation." (PMID 25115394, 2014). "Additionally, ATF6α has been reported to promote tumor metastasis through ENTPD5." (PMID 40223122, 2025). "ENTPD5/CD39L4, a soluble endoplasmic reticulum UDPase can also directly modulate tumor growth impacting N-glycosylation and cell metabolism and has been proposed as target for anti-cancer therapy." (PMID 30941139, 2019). "LNCaP cells with inducible shRNA against ENTPD5 showed reduced tumor burden after knockdown, and MDA-MB-231 xenografts also showed reduced tumor growth following knockdown." (PMID 31242188, 2019). "By using qRT-PCR and IHC, we demonstrated at mRNA and protein level a significant down-regulation of ENTPD5 from normal colon mucosa, through primary CRC tumor to liver metastases (both p<0.001)." (PMID 25115394, 2014). "ENTPD5 staining showed weak or no expression in immune cells, but was detected in tumor cells; however, the corresponding gene was not over expressed." (PMID 38773214, 2024). "The genomic data showed higher expression of ENTPD4 in tumor samples than in normal samples.On the other hand, ENTPD5 was not prominently expressed by immune cells, but was expressed at high levels in tumor cells." (PMID 38773214, 2024).
cancer (18 papers, 2013 to 2026). A tumor composed of atypical neoplastic, often pleomorphic cells that invade other tissues. "As such, ENTPD5 has been considered a potential proto-oncogene and a therapeutic target in cancer treatment." (PMID 41685236, 2026). "It has been reported that the expression of Entpd5 in several types of cancers resulted in altered cellular metabolism, increased survival and invasiveness as well as metastasis, and enhanced resistance to stress stimulators." (PMID 36824269, 2023). "ENTPD5 promotes the proliferation of cancer cells and is frequently overexpressed in cancerous tissues." (PMID 34782677, 2021). "Second, the altered metabolic state of cancer cells (i.e. the Warburg effect) affects nucleotide pools, and ENTPD5 helps to promote a balanced nucleotide pool compatible with the requirements of the cancer cell." (PMID 31242188, 2019). "ENTPD5 relieves ER stress in cancer cells by providing UMP for the UDP-glucose antiporter, allowing for more cycles of glycoprotein folding in the ER." (PMID 31242188, 2019). "ENTPD5 supports cancer growth by promoting the import of UDP-glucose, a metabolite used for protein glycosylation and hence proper glycoprotein folding, into the ER by providing the counter molecule, UMP, to the ER antiporter." (PMID 31242188, 2019). "ENTPD5’s promise as a target against cancer was demonstrated using inducible shRNA in xenograft models." (PMID 31242188, 2019). "These validated molecular probes provide at least two scaffolds for the further development of ENTPD5 inhibitors, and serve as an important step in probing the utility of targeting ENTPD5 to combat cancer cell proliferation." (PMID 31242188, 2019). "This work serves as an important step in designing new molecular probes for ENTPD5 as well as further probing the utility of targeting ENTPD5 to combat cancer cell proliferation." (PMID 31242188, 2019). "Since ENTPD5 resulted significantly down-regulated in our analysis, and another study provided support for downregulation during cancer progression, we decided to study the relationship between miR-182 and its predicted target gene ENTPD5." (PMID 23987127, 2013). "ENTPD5 is believed to support cancer growth via two mechanisms." (PMID 31242188, 2019). "ENTPD5 is overexpressed through two independent pathways in cancer cells." (PMID 31242188, 2019). "Further studies with these and additional ENTPD5 inhibitors will help to clarify whether ENPTD5 is a suitable new target for cancer therapy." (PMID 31242188, 2019). "Cancer cells showed strong and diffuse cytoplasmic staining of ENTPD5." (PMID 25794010, 2015). "ENTPD5 appears to promote protein glycosylation and folding in part by regulating UDP and UMP levels, thereby enhancing the survival and proliferation of somatic or cancer cells." (PMID 41685236, 2026). "Indeed, cancer cells showing elevated levels of ENTPD5, an ER UDPase, promotes aerobic glycolysis to increase ATP for protein N-glycosylation and refolding." (PMID 25681259, 2015). "Despite its cancer-supporting function, no small molecule inhibitors of ENTPD5 are commercially available, and few studies have been performed in tissue culture to understand the effects of chemical inhibition of ENTPD5." (PMID 31242188, 2019).
ENTPD5 also shares sentences with these, for which no sentence is quoted: adenocarcinoma (3 papers); adenoma (3); kidney damage (2); nephropathy (2); cervical cancer (1); Cirrhosis (1); colon tumors (1); colorectal adenoma (1); colorectal tumor (1); Glucose intolerance (1); hyperlipidemia (1); Insulin resistance (1); liver fibrosis (1); lung adenocarcinoma (1); metabolic disorders (1); metastatic cancer (1); metastatic melanoma (1); pancreatic ductal adenocarcinoma (1); prostate (1); prostate-tumor (1); renal fibrosis (1); Sepsis (1); testicular germ cell tumor (1); Ureteral obstruction (1).